SLC35D4 (solute carrier family 35 member D4)
Description:
Golgi-localized UDP-N-acetylglucosamine (UDP-GlcNAc) transporter that transports UDP-N-acetylglucosamine into Golgi lumen. Contributes to lysosomal targeting of NPC2, a key protein required for lysosomal cholesterol exiting, and that utilizes the mannose-6-phosphate (M6P) modification pathway for its lysosomal targeting.
Synonyms: C18orf45; TMEM241; MGC11386; FLJ44259; hVVT
Tractability: Antibody: UniProt predicts a signal peptide or a membrane-spanning region.
Gene: Protein-coding gene on chromosome 18 (23,197,144 to 23,437,971, reverse strand). Ensembl gene ENSG00000134490.
Subcellular location: Golgi apparatus, cis-Golgi network membrane
Subcellular location (Human Protein Atlas): Golgi apparatus; Vesicles
Gene Ontology:
Molecular function: protein binding; UDP-N-acetylglucosamine transmembrane transporter activity
Biological process: UDP-N-acetylglucosamine transmembrane transport
Cellular component: Golgi apparatus
Genetic constraint (gnomAD): Loss-of-function variants: 35 observed, 39.56 expected, observed/expected ratio (o/e) 0.88, 90% interval 0.68 to 1.17. The upper end of that interval is the gene's LOEUF score, 1.17, which puts it in group 5 of 6, group 1 being the genes least tolerant of losing a copy. Missense variants: 263 observed, 284.12 expected, observed/expected ratio (o/e) 0.93, 90% interval 0.84 to 1.02. Synonymous variants: 97 observed, 113.73 expected, observed/expected ratio (o/e) 0.85, 90% interval 0.72 to 1.01.
Homologues: Orthologues: chimpanzee TMEM241 (98% identical), macaque TMEM241 (90% identical), pig TMEM241 (88% identical), dog TMEM241 (85% identical), mouse Tmem241 (82% identical), rat Tmem241 (78% identical), rabbit TMEM241 (74% identical), tropical clawed frog tmem241 (66% identical), zebrafish tmem241 (34% identical), Drosophila melanogaster frc (19% identical), Caenorhabditis elegans sqv-7 (18% identical). Paralogues in human: SLC35D2 (21% identical), SLC35D1 (18% identical), SLC35E2B (17% identical), SLC35H1 (17% identical), SLC35E3 (17% identical), SLC35C1 (15% identical), SLC35E4 (15% identical), SLC35E1 (12% identical), SLC35D3 (12% identical).
Diseases named in the same sentence as SLC35D4 in open-access papers:
SLC35D4 is named in the same sentence as 4 diseases in open-access papers, as found by Europe PMC text mining. Sharing a sentence is not in itself a finding about the gene and the disease.
SLC35D4 shares sentences with these, for which no sentence is quoted: Obesity (2 papers); cancer (1); neurological disorders (1); osteoporosis (1).